APOE (apolipoprotein E)
Diseases named in the same sentence as APOE in open-access papers (continued):
Sharing a sentence is not in itself a finding about the gene and the disease.
Hypercholesterolemia (continued). "The combinatorial effects of cilostazol and probucol also attenuated hypercholesterolemia-induced exacerbation in ischemic brain injury via decreasing MCP-1 expression and CD11b and GFAP immune reactivity in the ischemic cortex from apolipoprotein E (ApoE) knockout mice." (PMID 27057275, 2016). "The apolipoprotein E (apoE) gene product is a cholesterol transport protein and a major ligand of the low density lipoprotein (LDL) receptor, which plays an important role in lipid metabolism, hypercholesterolemia, as well as nerve repair and regeneration." (PMID 26074879, 2015). "Evaluation of the 24-hour urine protein excretion revealed that neither hypercholesterolemia (ApoE Sham: 26.4 ± 3.5 mg/24 h) nor ovariectomy (C57 OVX: 33.7 ± 4.7 mg/24 h) resulted in altered proteinuria when compared to C57 Sham (25.1 ± 5.7 mg/24 h)." (PMID 25422135, 2014). "The novelty of the present study is that it was possible to reduce DNA damage in MNC and liver cells of apoE-/- mice by chronic inhibition of PDE5 with sildenafil, even under conditions of hypercholesterolemia, possibly by the same antioxidative mechanisms above commented." (PMID 23981672, 2013). "As a control, the cardiac lipid metabolism gene cluster was not induced by hypercholesterolemia because expression of the lipid metabolism genes was not different between young ApoE-/- mice (age 24 weeks, without heart failure signs) and age-matched B6 mice." (PMID 21711241, 2011). "In a model of hypercholesterolemia brought on by genetic deletion of apolipoprotein E, gonadal but not chromosomal sex had a significant effect on total plasma cholesterol and free fatty acids, with higher levels in gonadal males, as also occurs in wildtype mice." (PMID 38189044, 2023). "To conduct these investigations, we utilized mice lacking the apolipoprotein E gene (ApoE−/−), an established mouse model known to develop severe spontaneous hypercholesterolemia and atherosclerotic lesions in various blood vessels, including the aorta, similar to those found in humans." (PMID 37873768, 2023). "Lack of apoE in mice was previously shown to create hypercholesterolemia and restoring plasma apoE levels could improve cognitive functions and partially alleviated synaptic deficits in apoE deficient mice." (PMID 35418601, 2022). "Considering that the blood cholesterol levels were much lower than those in high-cholesterol diet-fed apoE-deficient mice and wild-type mice carrying gain-of-function mutations of PCSK9, hypercholesterolemia is not likely to contribute to the augmented AAA development in O-HFD." (PMID 34571873, 2021). "ApoE deficiency in macrophages may contribute to hypercholesterolemia, while the lack of LDL-R in hepatocytes is responsible for hypercholesterolemia in ApoE−/- and LDL-R−/− models." (PMID 34975474, 2021). "Rosuvastatin did not, however, reduce the hypercholesterolemia in the SR-B1/apoE dKO mice; instead, plasma total cholesterol levels were, unexpectedly, substantially increased by rosuvastatin treatment; however, the reasons for this effect remain unclear." (PMID 30356742, 2018). "Therefore, despite other studies have not detected age-related neurological abnormalities in ApoE−/− mice our result strongly suggests that hypercholesterolemia during aging is related with these changes." (PMID 29510495, 2018). "In addition, apoE−/− mice showed higher cytotoxicity, evaluated by the ratio of PCE/NCE, compared with WT mice, suggesting that hypercholesterolemia presents cytotoxic action in bone marrow cells of atherosclerotic mice and sildenafil treatment completely abolishes this toxicity." (PMID 27229150, 2016).
Hypercholesterolemia (continued). "However, the critical role of CCR7 in atheroregression was not confirmed in the model in which overexpression of ApoE was used to reverse hypercholesterolemia." (PMID 24741577, 2014). "Therefore in ApoE−/− mice hypercholesterolaemia alone does not appear sufficient to significantly affect gap junctions and therefore they are unlikely to be contributing to the reduced vasorelaxation we observe." (PMID 24630173, 2014). "Moreover, there is evidence that the impaired endothelial NO-dependent relaxation response to ACh in apoE-/- mice is not determined by hypercholesterolemia alone." (PMID 22082357, 2011). "Hypercholesterolemia levels of ApoE mice were not affected by ovariectomy." (PMID 20482882, 2010). "Besides, compared to C57BL/6 mice, ApoE−/− mice on a standard diet naturally develop hypercholesterolemia and may, between 11–21 weeks, show signs of smaller, absent foam cells or calcified deposits in the carotid arteries or aorta." (PMID 39175877, 2024). "All together, these findings suggest that hypercholesterolemia did not exert marked effects on endothelial function in the ophthalmic artery, which contrasts with our previously published findings in retinal arterioles, where pronounced endothelial dysfunction was observed in ApoE−/− mice." (PMID 37873768, 2023). "Moreover, knockout mice lacking ApoE developed extreme hypercholesterolemia after a high-fat diet." (PMID 28086795, 2017). "Hence, we anticipated that the hypercholesterolemia, and concomitant alterations in plasma proteins and apolipoproteins could interfere with the successful endothelial delivery of the siRNAs with the 7C1 LNP, observed under conditions of regularly circulating apoE in the WT mice." (PMID 40093962, 2025). "Medullary ERα protein expression (B) was affected by neither hypercholesterolemia nor ovariectomy (C57 Sham: 1.00 ± 0.04; C57 OVX: 1.03 ± 0.02; ApoE Sham: 0.95 ± 0.06; ApoE OVX: 1.00 ± 0.03 au)." (PMID 25422135, 2014). "Although reports show that SOD protein expression is unaltered in aorta that are exposed to hypercholesterolemia, SOD mimetics reduced •O2- production and partially normalized relaxation in response to ACh in aortic and carotid arteries from apoE-/- mice." (PMID 22082357, 2011). "In contrast, Western diet feeding induced only a modest, non-significant increase in IFN-γ expression in splenic γδT cells of ApoE KO mice, and γδT cell IFN-γ expression was similar in wild-type mice that do not develop hypercholesterolemia or aortic lesions after Western diet feeding." (PMID 25313857, 2014).
hyperlipidemia (450 papers, 2005 to 2026). "For APOE we additionally tested for association with hyperlipidaemia and for APP and MAPT we tested for associations with mental health and epilepsy." (PMID 41123760, 2025). "Initially studied in hyperlipidemia, APOE encodes a 317‐amino‐acid protein, apoE, that includes an 18‐residue signal peptide." (PMID 39031528, 2024). "Another meta-analysis of 59 studies including 13,843 subjects revealed that the ε4 and ε2 alleles of the apoE gene are risk factors for hyperlipidemia." (PMID 38507115, 2024). "Biochanin A activates PPARγ/LXRα/ABC transporter and PPARγ/heme oxygenase 1 signaling pathways to suppress hyperlipidemia-induced inflammation in ApoE-deficient mice." (PMID 38699583, 2024). "The cardioprotective effects of CoQ10 have been previously documented against hyperlipidemia-induced cardiac damage in apolipoprotein E-deficient mice, and doxorubicin-induced cardiotoxicity in rats." (PMID 37860674, 2023). "We discovered that high-cholesterol diets increased serum creatine kinase levels in ApoE−/− mice, which suggests that hyperlipidemia also causes muscle damage." (PMID 37091976, 2023). "This study aimed to investigate the effects of exercise on hyperlipidemia-induced cardiac damage in apolipoprotein E-deficient (ApoE−/−) mice." (PMID 37277452, 2023). "Spontaneous hyperlipidemia (Apoeshl) mice have been shown to develop due to apolipoprotein E deficiency due to mutations in the apolipoprotein E gene." (PMID 37396111, 2023). "APOE deficiency is associated with aging-related changes and hyperlipidemia and promotes NAFLD in mice." (PMID 38250971, 2023). "Combing streptozotocin with hyperlipidaemia by knocking out Apoe (encoding apolipoprotein E) accelerates and worsens renal injury in C57BL/6 mice." (PMID 35698028, 2022). "More recently, a case report suggesting a 28-year-old man presenting with severe proteinuria and hyperlipidemia had compound heterogeneous mutations of the APOE gene inherited from his mother (p.Arg50His) and father (APOE Kyoto)." (PMID 35602473, 2022). "Meyrelles and colleagues performed a study on old apolipoprotein E-deficient mice, which develop hyperlipidemia similar to humans, and showed that they had poorer endothelial function than younger mice." (PMID 36231632, 2022). "Consistent with previous reports, ApoE−/− mice fed with high-fat diets are susceptible to hyperlipidemia." (PMID 36498935, 2022). "Apolipoprotein E (ApoE) is essential for lipid and cholesterol metabolism and its absence results in hyperlipidemia; thus, ApoE- deficient mice are the most used animal model for studying hyperlipidemia." (PMID 36139398, 2022). "The therapeutic potential of GMSCs in the periodontitis treatment was demonstrated in a study conducted by Liu and coworkers on the periodontitis model created in mice that were apolipoprotein E-deficient (ApoE−/−) with hyperlipidemia." (PMID 36139367, 2022). "ApoE−/− mice fed with a high-fat diet are indeed susceptible to hyperlipidemia were corresponding to previous reports." (PMID 35833033, 2022). "3C ameliorated high-fat diet-induced body weight gain, hyperlipidemia, and atherosclerotic plaque burden in apolipoprotein E-deficient (ApoE-/-) mice after 10 weeks of treatment." (PMID 33901014, 2021). "Meta-analysis of the data indicated that APOA5–1131 T > C, APOA1 -75 bp, APOB XbaI, and APOE gene polymorphisms were significantly associated with hyperlipidemia, with OR values of 1.996, 1.228, 1.444, and 1.710, respectively." (PMID 33836655, 2021). "The APOE ε3 allele was used as a reference to analyze the relationship between alleles and hyperlipidemia." (PMID 33836655, 2021).
hyperlipidemia (continued). "The STZ-induced T1D in ApoE KO mice is a model of combined hyperglycemia and hyperlipidemia widely used for studying pathogenic mechanisms and nephroprotective therapies in DN because of similarities with human disease." (PMID 34943023, 2021). "Given the background of the ApoE-deficient mouse model of hyperlipidemia, Rac2 deletion resulted in elevated circulating IL-1β in blood plasma from mice on a cholesterol-supplemented high-fat diet." (PMID 34831028, 2021). "The APOE gene is co-coded by the three alleles, ε2, ε3, and ε4, for which 30 case control studies were studied that included 5208 cases in the hyperlipidemia group and 6406 cases in the control group." (PMID 33836655, 2021). "Of the existing apolipoprotein candidate genes, researchers have correlated APOA1, APOA5, APOB, and APOE gene polymorphisms with hyperlipidemia." (PMID 33836655, 2021). "Apolipoprotein E-deficient (ApoE−/−) mice, a well-established animal model of hyperlipidemia, have been used extensively to study the effects of atherosclerosis and renal injury." (PMID 34409103, 2021). "Meta-analysis of the data indicated that the C allele of APOA5 1131 T > C, the A allele at APOA1-75 bp, the APOB XbaI T allele, and the ε2 and ε4 allele of APOE were each a risk factor for susceptibility for hyperlipidemia." (PMID 33836655, 2021). "This study investigated the effect of exercise on hyperlipidemia-induced neuronal injury in apolipoprotein E-deficient (ApoE−/−) mice." (PMID 34409103, 2021). "(2009) reported that GG genotype of APOE rs405509 is significantly associated with hyperlipidemia in Caucasian sample population." (PMID 33737636, 2021). "There is evidence that ApoE ɛ4 alleles and hyperlipidemia play a crucial role in the relationship between AD and CHD." (PMID 32587611, 2020). "In particular, rs7412, the marker of the APOE-ε2 allele, was associated with lower risk of hyperlipidemia in both the Geisinger and VUMC-EA samples." (PMID 32711518, 2020). "Due to important roles of both ApoE and LDL receptor in the regulation of cholesterol metabolism, using ApoE-/- rabbits together with LDL receptor-deficient WHHL rabbits appears to be promising for modelling human hyperlipidemia." (PMID 32428130, 2020). "Although the three APOE alleles appear to be determinant for the plasma lipidemia, other apoE-independent polymorphisms found in the cluster contribute to lipid homeostasis." (PMID 31779116, 2019). "The strongest evidence of an association with hyperlipidemia has been found for Leu167del of apolipoprotein E." (PMID 31795497, 2019). "In ApoE knockout (ApoE−/−) mice fed with a high-fat diet, hyperlipidemia has been shown to exacerbate neuronal death and loss upon ischemic stroke induction." (PMID 29867540, 2018). "A major undesirable effect associated with increased peripheral wild-type (wt) APOE expression is the induction of severe hypertriglyceridemia and subsequently combined hyperlipidemia." (PMID 29770778, 2017). "With respect to hyperlipidemia, apolipoprotein E (apoE)-deficient mice, which develop hyperlipidemia and atheroscleorosis when maintained on a high-fat diet, exhibit impaired wound healing after MI." (PMID 29163503, 2017). "In conclusion, catK deficiency almost completely blunted the increased vascular remodeling response of apoE-/- mice to flow cessation, possibly by correcting hyperlipidemia-associated pro-inflammatory effects on the peripheral immune response." (PMID 27636705, 2016). "In the present study, we have determined the effect of TSP1 deficiency on the development of obesity and hyperlipidemia induced macro and micro-vascular complications in ApoE-/- mice." (PMID 25803585, 2015). "In mice, ApoE deficiency causes the formation of atherosclerotic lesions, hyperlipidemia, and chronic inflammation." (PMID 26167199, 2014).
hyperlipidemia (continued). "APOE knockout mice do also exhibit an enhanced susceptibility to endotoxemia, which supports the concept that the presence of hyperlipidemia renders these mice more prone for (lethal) inflammation." (PMID 24265824, 2013). "Apolipoprotein E deficient (ApoE−/−) mice develop severe hyperlipidemia under normal diet condition." (PMID 23977160, 2013). "These atheroprotective biological functions of ApoE are corroborated by the hyperlipidaemia and atheroma seen in ApoE-deficient (ApoE−/−) mice." (PMID 22645694, 2012). "In conclusion, results of our study demonstrate that macrophages including liver-associated Kupffer cells raise plasma apoE levels in response to diet-induced hyperlipidemia." (PMID 22606237, 2012). "Genetically engineered phenotypes of mice that are deficient in apolipoprotein E (ApoE(-/-) mice) spontaneously develop severe hyperlipidemia and atherosclerotic lesions at the arterial wall." (PMID 21134260, 2010). "Type III hyperlipidemia (Type III HLP) is associated with homozygosity for the ε2 allele of the APOE gene." (PMID 17727701, 2007). "In contrast, female apoE KO rabbits showed a significant increase in plasma TG levels but had similar plasma TC levels as the WT control group, suggesting that males are more susceptible to diet-induce hyperlipidemia than females in the setting of apoE deficiency." (PMID 39087075, 2024). "Compared with ApoE-deficient mice, spontaneous Apoeshl mice could be more useful as a model for hyperlipidemia, arteriosclerosis, and AD." (PMID 37396111, 2023). "On the other hand, ApoE (E2) and (E4) are associated with hyperlipidemias." (PMID 36904211, 2023). "APOE knockout mice were also susceptible to a variety of pathogens, further verifying that hyperlipidemia could affect immune function through a series of signaling pathways." (PMID 34544385, 2021). "Knockout of the ApoE gene in mice caused low-density lipoprotein metabolism disorders with low-density lipoproteins oxidized and deposited in blood vessels, ultimately leading to severe hyperlipidemia and atherosclerotic lesions." (PMID 34566648, 2021). "In experimental research, one of the frequently used animal models of hyperlipidemia is the apolipoprotein E-deficient murine model (Apoe-/-, apolipoprotein E is one of the protein components of lipoproteins such as LDL and is involved in lipid transport to tissues)." (PMID 34868060, 2021). "The LRP1 NPxY mutation has been shown to improve hyperlipidemia in ApoE−/− mice." (PMID 33500241, 2021). "Moreover, systemic genetic ablation of ACKR3 was shown to cause hyperlipidemia in Apolipoprotein E deficient (Apoe−/−) mice, whereas its activation through CCX771 injections in mice decreased serum cholesterol and triglyceride levels." (PMID 33917642, 2021). "Moreover, chronic treatment with TCEE attenuated hyperlipidemia, systemic and aortic inflammatory response, and the atherosclerotic lesions in apolipoprotein E-deficient mice." (PMID 32102326, 2020). "Moreover, rs429358, the marker of the APOE-ε4 allele, was associated with increased risk of hyperlipidemia in all of the EHR-derived datasets." (PMID 32711518, 2020). "We demonstrated that deletion of apoE per se was associated with hyperlipidemia via elevations in plasma levels of both cholesterol and triglycerides; however, little consequent effect on urinary albumin excretion, plasma cystatin C levels or glomerular matrix accumulation were observed." (PMID 32581831, 2020). "Thus, to be more clinically relevant, we also used hyperlipidemia model by crossing Il12rb2−/− mice with hyperlipidemia-conditioned apolipoprotein E deficient (ApoE−/−) mice." (PMID 33154757, 2020). "SRBI−/− crossed with mice harbouring the hypomorphic ApoE allele ApoER61h/h display features of hyperlipidaemia upon a high-fat diet leading to coronary plaques, partially occlusive coronary stenoses, spontaneous MI and reduced survival, closely resembling human coronary artery disease." (PMID 33258000, 2020).